ZNRF2 (zinc and ring finger 2)
Description:
E3 ubiquitin-protein ligase that plays a role in the establishment and maintenance of neuronal transmission and plasticity. Ubiquitinates the Na(+)/K(+) ATPase alpha-1 subunit/ATP1A1 and thereby influences its endocytosis and/or degradation. Acts also as a positive regulator of mTORC1 activation by amino acids, which functions upstream of the V-ATPase and of Rag-GTPases. In turn, phosphorylation by mTOR leads to its inhibition via targeting to the cytosol allowing a self-regulating feedback mechanism.
Synonyms: RNF202
Tractability: Antibody: UniProt places it where antibodies can reach, with high confidence; its Gene Ontology location is reachable by antibodies, with high confidence. PROTAC: ubiquitination databases record sites on it; its protein half-life has been measured.
Gene: Protein-coding gene on chromosome 7 (30,284,418 to 30,370,457, forward strand). Ensembl gene ENSG00000180233.
Subcellular location: Endosome membrane; Lysosome membrane; Presynaptic cell membrane; Cytoplasm
Subcellular location (Human Protein Atlas): Nucleoplasm; Vesicles; Nucleoli fibrillar center
Pathways (Reactome):
Immune System: Antigen processing: Ubiquitination & Proteasome degradation
Gene Ontology:
Molecular function: ubiquitin protein ligase activity
Biological process: positive regulation of autophagosome-lysosome fusion; proteasome-mediated ubiquitin-dependent protein catabolic process; protein K48-linked ubiquitination; protein ubiquitination
Cellular component: cytoplasm; cytoplasmic vesicle membrane; plasma membrane; protein-containing complex; cytosol; membrane; endosome membrane; lysosomal membrane; presynaptic membrane
Genetic constraint (gnomAD): Loss-of-function variants: 7 observed, 4.26 expected, observed/expected ratio (o/e) 1.64, 90% interval 0.85 to 1.95. That is too few expected variants to judge how well the gene tolerates losing a copy. Missense variants: 292 observed, 157.91 expected, observed/expected ratio (o/e) 1.85, 90% interval 1.67 to 1.97. Synonymous variants: 135 observed, 76.04 expected, observed/expected ratio (o/e) 1.78, 90% interval 1.54 to 1.96.
Homologues: Orthologues: chimpanzee ZNRF2 (97% identical), dog ZNRF2 (91% identical), pig ZNRF2 (91% identical), macaque ZNRF2 (86% identical), rat Znrf2 (85% identical), mouse Znrf2 (81% identical), zebrafish znrf2b (64% identical), tropical clawed frog znrf2 (58% identical), Drosophila melanogaster CG14435 (44% identical), Caenorhabditis elegans Y71F9AL.10 (34% identical). Paralogues in human: ZNRF1 (45% identical), RNF11 (17% identical).
Diseases named in the same sentence as ZNRF2 in open-access papers:
ZNRF2 is named in the same sentence as 27 diseases in open-access papers, as found by Europe PMC text mining. Sharing a sentence is not in itself a finding about the gene and the disease. The quoted sentences say what the papers report.
osteosarcoma (3 papers, 2017 to 2024). A usually aggressive malignant bone-forming mesenchymal neoplasm, predominantly affecting adolescents and young adults. "TRIM22 inhibits osteosarcoma progression by promoting proteasomal degradation of zinc and ring finger 2 (ZNRF2) independent of goblet-like ECH-associated protein 1 (KEAP1), resulting in autophagic death of sarcoma cells." (PMID 38225560, 2024).
papillary thyroid cancer (3 papers, 2019 to 2022). "TTN-AS1 mediates miR-153-3p to accelerate malignant behaviors by mediating ZNRF2 in papillary thyroid cancer." (PMID 34141611, 2021). "Furthermore, miR-153 regulates the expression level of an E3 ubiquitin ligase, Zinc and ring finger 2 (ZNRF2), which is implicated in the activity of PI3K/Akt/mTOR pathway in papillary thyroid cancer." (PMID 36158686, 2022). "In papillary thyroid cancer, TTN-AS1 serves as a ceRNA for miR-155-3p and facilitates the expression of zinc and ring finger 2, thus, promoting cellular proliferation, migration, invasion, and epithelial–mesenchymal transition." (PMID 31525734, 2019).
hepatocellular carcinoma (2 papers, 2015 to 2023). A malignant tumor that arises from hepatocytes. "The results of this study indicated that ZNRF2 is highly expressed in most tumours compared to the control group, which was further confirmed in hepatocellular carcinoma." (PMID 37551845, 2023). "The miR-550 gene is located in the intronic region of the Znrf2 gene on human chromosome 7p14.3, and expressed in multiple cancers including hepatocellular carcinoma." (PMID 26329304, 2015). "Additionally, we explored potential molecular mechanisms of ZNRF2 in tumours, finding that it increases in hepatocellular carcinoma (HCC) tissues and that inhibiting its expression through ZNRF2 siRNA can limit HepG2 cell proliferation." (PMID 37551845, 2023). "Furthermore, we used single‐cell sequencing data to analyse the expression and distribution of ZNRF2 in hepatocellular carcinoma (HCC) and further explore the function of ZNRF2 in the HepG2 cell line." (PMID 37551845, 2023). "In order to investigate how ZNRF2 affects the function of tumour cells, we conducted an examination of ZNRF2 expression patterns in four samples of hepatocellular carcinomas (HCC) tissues and four corresponding adjacent noncancerous tissues (ANCT) using Western blotting." (PMID 37551845, 2023).
Acute myeloid leukaemia (1 paper, 2023). "High expression of ZNRF2 was in DLBC (Lymphoid neoplasm diffuse large B‐cell lymphoma), LAML (Acute myeloid leukaemia), OV (Ovarian serous cystadenocarcinoma) and THYM (Thymoma) (p < 0.05), low expression of ZNRF2 was in TGCT (Testicular germ cell tumours) (p < 0.05)." (PMID 37551845, 2023).
bladder cancer (1 paper, 2023). "We found that the frequency (0.5%) of variants in ZNRF2 was highest in bladder cancer with ‘mutation’." (PMID 37551845, 2023).
breast carcinoma (1 paper, 2023). "We found that the expression levels of total ZNRF2 protein were higher in breast cancer, LUAD and UCEC tissues compared with normal tissues." (PMID 37551845, 2023).
colon adenocarcinoma (1 paper, 2023). "By contrast, ZNRF2 showed low expression in COAD (Colon adenocarcinoma), KICH (Kidney chromophobe), KIRC (Kidney renal clear cell carcinoma) and READ (Rectum adenocarcinoma) (p < 0.001)." (PMID 37551845, 2023). "We observed that ZNRF2 was significantly negatively correlated with TMB in two tumours: COAD (p < 0.001), COADREAD (Colon adenocarcinoma/Rectum adenocarcinoma oesophageal carcinoma) (p < 0.001)." (PMID 37551845, 2023).
lung carcinoma (1 paper, 2023). "Using the Kaplan–Meier mapping tool to analyse patient survival data, we found correlations between high levels of ZNRF2 and poor first progression (FP) (p = 0.0017) for lung cancer." (PMID 37551845, 2023).
non-small cell lung carcinoma (1 paper, 2023). A group of at least three distinct histological types of lung cancer, including non-small cell squamous cell carcinoma, adenocarcinoma, and large cell carcinoma. "In non‐small cell lung cancer, ZNRF2 upregulates mTOR protein expression to promote cell proliferation and inhibit cell apoptosis." (PMID 37551845, 2023). "Recent research has revealed the crucial role that Zinc and ring finger 2 (ZNRF2) play in the progression of non‐small cell lung cancer (NSCLC) by controlling cell growth and death." (PMID 37551845, 2023).
cancer (3 papers, 2015 to 2023). A tumor composed of atypical neoplastic, often pleomorphic cells that invade other tissues. "High expression of ZNRF2 was associated with poor prognosis of DFS (disease‐free survival) for cancers including GBM (p = 0.035) and LGG (p = 0.00056)." (PMID 37551845, 2023). "Due to mutations in genes are critical to the development of cancer, we further analysed the genetic alterations of ZNRF2 in tumour samples." (PMID 37551845, 2023). "Additionally, we have investigated the genetic variations, immune response and molecular pathways associated with ZNRF2 in cancer." (PMID 37551845, 2023). "Next, we investigated whether mutations in ZNRF2 affect the survival prognosis of cancer patients." (PMID 37551845, 2023). "Our findings indicate that ZNRF2 is generally expressed at higher levels in tumours than in normal tissues, and in some cancers, its levels correlate positively with disease stage, potentially predicting a poor prognosis for patients." (PMID 37551845, 2023). "Previous studies have shown that the ZNRF2 involves a series of fundamental different physiological processes under multiple diseases, including cancer." (PMID 37551845, 2023). "We also discovered genetic changes in ZNRF2 among cancer patients, as well as its relationship with cancer‐related fibroblasts, endothelial cells and immune cell infiltration." (PMID 37551845, 2023). "According to the expression levels of ZNRF2, the cancer cases were divided into high‐expression and low‐expression groups." (PMID 37551845, 2023). "Overall, our study provides a comprehensive overview of ZNRF2's oncogenic roles across various cancers." (PMID 37551845, 2023). "We also used the GEPIA2 tool to evaluate the correlation between ZNRF2 expression and the pathological stages of cancers." (PMID 37551845, 2023). "Since the biological function of ZNRF2 was very recently discovered, its participation in the cancer growth, progress and metastasis remain largely unexplored." (PMID 28416774, 2017). "However, previous studies about ZNRF2 are still limited to a few cancer types, and further exploration is needed to clarify its role in tumours." (PMID 37551845, 2023). "Our aim is to conduct a thorough analysis of ZNRF2 across different types of cancer." (PMID 37551845, 2023). "The expression of ZNRF2 in LIHC (p < 0.05) was positively correlated with cancer‐associated fibroblasts, while the expression of ZNRF2 in TGCT (p < 0.05) was negatively correlated with cancer‐associated fibroblasts." (PMID 37551845, 2023). "Our study sought to investigate the impact of ZNRF2 on diverse human tumours, as well as the molecular pathways involved, using databases such as TCGA (The Cancer Genome Atlas), GEO (Gene Expression Omnibus) and the Human Protein Atlas (HPA), as well as several bioinformatic tools." (PMID 37551845, 2023). "However, a comprehensive analysis of ZNRF2's role in cancer as a whole has yet to be conducted." (PMID 37551845, 2023). "Although a diverse role of miR-100 has been reported in different cancers, its effects on ZNRF2 expression specifically in OS has not been reported." (PMID 28416774, 2017).
tumor (2 papers, 2017 to 2023). "In this study, we aimed to study the molecular mechanisms that underlie the regulation of the tumor growth of OS by miR-100 and ZNRF2." (PMID 28416774, 2017). "We observed that ZNRF2 was significantly associated with MSI in 11 tumours." (PMID 37551845, 2023). "In this study, we aimed to provide an analysis indicated a potential role of human ZNRF2 in tumours (NM_147128.4 for mRNA or NP_667339.1 for protein)." (PMID 37551845, 2023). "To accomplish this, we have utilized the TCGA, CPTAC and GEO databases to examine the gene expression and protein levels of ZNRF2 within tumours." (PMID 37551845, 2023). "To summarize, our research reveals that ZNRF2 is significantly involved in the development of different types of tumours." (PMID 37551845, 2023). "Next, we investigated the relationship between the expression of ZNRF2 and TMB (Tumour mutational burden) and MSI (Microsatellite instability)." (PMID 37551845, 2023). "In our research, we discovered a positive correlation between the expression of ZNRF2 and mTOR in various types of tumours." (PMID 37551845, 2023). "In this study, we analysed the expression levels of ZNRF2 in various human tumours using various databases, such as TCGA, and we explored the ZNRF2 to survival status, genetic changes, immune infiltration and related molecular pathways in tumours." (PMID 37551845, 2023). "We showed the correlation of ZNRF2 expression levels with MTOR in some tumours, such as DLBC, KIRP, LGG, SKCM, THYM and UVM (p < 0.001)." (PMID 37551845, 2023). "Next, we used the TCGA and GEO data sets from the GEPIA2 tool to investigate the correlation between ZNRF2 expression and prognosis of different tumour patients." (PMID 37551845, 2023). "We further used the CPTAC database to assess differences in total ZNRF2 protein expression between tumour and normal tissues." (PMID 37551845, 2023). "We used the TISIDB tool to analyse the relationship between ZNRF2 expression and tumour‐infiltrating lymphocytes, immune‐stimulators, MHC molecules, chemokines and chemokine receptors." (PMID 37551845, 2023). "We also compared the differences in ZNRF2 phosphorylation levels between normal and primary tumour tissues." (PMID 37551845, 2023). "Next, we analysed the differential expression of ZNRF2 in tumours and adjacent normal tissues in the TCGA database." (PMID 37551845, 2023). "Thus, further experimentation is necessary to investigate any potential correlation between alterations in ZNRF2 protein levels and phosphorylation levels and the immunosuppressive effects in the tumour microenvironment." (PMID 37551845, 2023). "Heat map in most tumour types showed significant positive correlations of the MTOR with ZNRF2." (PMID 37551845, 2023). "Furthermore, our analysis revealed that the expression level of ZNRF2 is positively correlated with the immunosuppressive molecule CD274 in various tumours, and in THCA, it is positively correlated with Tregs." (PMID 37551845, 2023). "Moreover, our study found that the phosphorylation level of ZNRF2 also exhibits abnormal changes in tumours, especially BRCA, KIRC, PAAD, LIHC, HNSC and GBM." (PMID 37551845, 2023). "In conclusion, genetic changes in ZNRF2 are critical for developing the described tumours." (PMID 37551845, 2023). "Next, we analysed the relationship between ZNRF2 and mTOR signalling pathway in TCGA tumours." (PMID 37551845, 2023). "Notably, in some tumour types such as KIRC, low expression of ZNRF2 was associated with a poor prognosis of disease‐free survival (p = 0.03)." (PMID 37551845, 2023). "We have explored the potential molecular mechanisms that ZNRF2 may use to promote the development of tumours." (PMID 37551845, 2023). "To explore the function of ZNRF2 through various tumour types in a pancancer analysis, we take advantage of gene sequencing technology and bioinformatics, which provide new insights into tumour research." (PMID 37551845, 2023).
tumor (continued). "This contributes to our understanding of the critical role that ZNRF2 plays in tumour development." (PMID 37551845, 2023). "This indicated that the interaction between ZNRF2 and mTOR may be involved in tumour growth." (PMID 37551845, 2023). "Therefore, we hypothesized that ZNRF2 mediates the regulatory network of the mTOR signalling pathway and thus might influence the molecular mechanisms of tumour development." (PMID 37551845, 2023). "Furthermore, we applied the TIMER, CiberSort, CiberSort‐ABS, TID, XCell, MCPCOUNTER, QUANTISEQ and EPIC algorithms to explore the correlation between the infiltration levels of different immune cells and endothelial cells in various tumour types and ZNRF2 expression." (PMID 37551845, 2023). "Poor OS (overall survival) prognosis with high ZNRF2 expression in two tumour types: CESC (p = 0.034), LGG (p = 0.00049) and poor OS prognosis with low ZNRF2 expression in two tumour types: KIRC (p = 1.3e‐06), SKCM (p = 7e‐04)." (PMID 37551845, 2023). "For tumours without normal tissue data as control, we further used the GTEx data set to analyse the different expression level of ZNRF2 in tumours and normal tissues." (PMID 37551845, 2023). "Negative or moderate staining for ZNRF2 in normal tissues (breast, lung, stomach, liver and uterine) and moderate or vigorous positivity in the corresponding tumour tissues were in agreement with the results of the TCGA database." (PMID 37551845, 2023). "This suggested that targeting ZNRF2 may inhibit immunosuppressive cells in THCA, thereby reversing the immunosuppressive microenvironment and enhancing the ability of anticancer immune cells to kill tumour cells." (PMID 37551845, 2023).
ZNRF2 also shares sentences with these, for which no sentence is quoted: atherosclerosis (1 paper); cervical squamous cell carcinoma (1); cholangiocarcinoma (1); diffuse large B-cell lymphoma (1); gastric cancer (1); Kidney chromophobe (1); liver cancer (1); lymphoid neoplasm (1); ovarian serous cystadenocarcinoma (1); pancreatic adenocarcinoma (1); prostate adenocarcinoma (1); rectum adenocarcinoma (1); sarcoma (1); tauopathy (1); Testicular germ cell tumours (1); thymoma (1).